ATM (ATM serine/threonine kinase)
Diseases named in the same sentence as ATM in open-access papers (continued):
Sharing a sentence is not in itself a finding about the gene and the disease.
Fanconi anemia (continued). "Moreover, E2F2 is possibly involved in CRC tumorigenesis and development via modulating ATR pathway, ATM signalling pathway, mismatch repair, base excision repair, homologous recomibination, Fanconi Anemia pathway, multicancer invasiveness signature, cancer stem cells and immune infiltrating cells." (PMID 35069909, 2022). "Transcriptional profiling during bleomycin challenge identified 18 DDR genes with relatively higher expression in PET-exposed cells compared to passage-matched controls, encompassing HR, BER, ATM/ATR signaling, the Fanconi anemia pathway, and apoptosis." (PMID 42278555, 2026). "This pathway involves multiple proteins, including BRCA1, BRCA2, proteins of the MRN complex, CtIP, RAD51, ATM, H2AX, PALB2, RPA, RAD52, and proteins of the Fanconi anemia pathway." (PMID 38236558, 2024). "Genes that were upregulated by the presence of R-loops in HPV positive cells included those in the DNA damage repair such as ATM, ATRX, and members of the Fanconi Anemia pathway." (PMID 39178326, 2024). "A highlight has been given to the role of germline monoallelic variants in cancer predisposition in genes involved in the recognition and repair of DNA damage, such as the ATM, PALB2, and Fanconi anemia genes." (PMID 35495172, 2022). "HRR alterations involve Fanconi anemia genes (PALB2, FANCA, FANCL, FANCI, FANCC), core RAD genes (RAD50, RAD51, RAD51B, RAD51C) as well as DNA damage response genes (ATM, ATR, CHEK1, CHEK2)." (PMID 36531003, 2022). "In our work, transcriptomic studies revealed that functions involved in DNA damage such as those classified as ATM, ATR, Fanconi Anemia, and BARD1 pathways are clearly dysregulated in breast tumors, particularly in the basal-like and HER2 subtype." (PMID 33925616, 2021). "Genes included in different pathways, such as ATM/ATR, BARD1, and Fanconi Anemia, which are involved in the DNA damage response, were selected and confirmed using molecular alterations data contained at cBioportal." (PMID 33925616, 2021). "Evaluation of tumor tissue found additional somatic mutations in BRCA1/2 (3%), EMSY (8%), PTEN (7%), RAD51C (3%), ATM/ATR (2%) and Fanconi anemia genes (5%)." (PMID 28250960, 2017). "HR operates during the S and G2 phases of the cell cycle and relies on many proteins including BRCA1 and BRCA2, proteins of the MNR complex (MRE11/RAD50/NBS1), CtIP, MRE11, RAD51, ATM, H2AX, PALB2, RPA, RAD52 and proteins of the Fanconi anemia pathway." (PMID 28250960, 2017). "In fact, loss of most genes involved in DNA damage checkpoints or DNA damage repair, such as ATM, ATR, BRCA1, BRCA2, Fanconi anemia genes, lead to increased sensitivity to genotoxic agents." (PMID 15494723, 2004). "Our studies show that genes like ATM, ATRX, RAD51C, along with members of the Fanconi Anemia pathway (FANC-B, C, E, I, L, and M), and SETD2, the methyltransferase regulating H3K36me3, were all associated with the combination of H3K36me3, γH2AX and enhanced R-loops." (PMID 39178326, 2024). "Other defects in homologous recombination repair genes, such as EMSY, RAD51, ATM, ATR, Fanconi anemia, BARD1, BRIP1, PALB2, RB1, NF1, CDKN2A, and the suppression of BRCA1 transcriptional activation through gene methylation, are associated with homologous recombination deficiency (HRD)." (PMID 32679669, 2020). "Besides, some other core components of HR such as RAD51 recombinase (RAD51), ATM serine/threonine kinase (ATM), ATR serine/threonine kinase (ATR), partner and localizer of BRCA2 (PALB2), and Fanconi anemia gene family are determinants of intact HR as well." (PMID 31737426, 2019).
Fanconi anemia (continued). "Indeed, this NEK2 inhibition is dependent of ATM, a protein that, along with ATR, are master controllers of cell cycle and DNA repair, the main pathway deregulated in Fanconi Anemia." (PMID 31266445, 2019). "Replication stress is known to induce DNA damage due to the stalled or collapsed forks, which then activates ATM/ATR-mediated cell cycle checkpoint responses to promote fork stability and restart thorough Rad18 and Fanconi anemia (FA) DNA repair pathways (monoubiquitinated FANCD2)." (PMID 25742788, 2015). "In contrast, TGF‐β has also been shown to protect against genomic instability by enhancing nonhomologous end‐joining repair, ATM activity, and the SMAD3/β2spectrin/Fanconi anemia DNA repair pathway." (PMID 32073751, 2020). "These genes include the Fanconi anemia pathway genes: FANCA, PALB2, BRIP1, RAD51C and XRCC2 and non-Fanconi anemia genes: ATM, CHEK2, NBN, RAD50, RAD51B, and RAD51D." (PMID 28202063, 2017). "Some of these non-core genes include ARID1A, ATM, RAD51, CHEK2, and the Fanconi anemia genes." (PMID 39860372, 2025).
glioblastoma (79 papers, 2010 to 2026). The most malignant astrocytic tumor (WHO grade IV). "Studies have demonstrated that inhibiting key DNA repair proteins, such as ATR, ATM, and DNA-PK, increases the susceptibility of glioblastoma cells to radiation-induced damage." (PMID 40652278, 2025). "In glioblastoma, β-elemene’s ability to enhance both radiosensitivity and chemosensitivity was linked to its inhibition of the ATM signaling pathway." (PMID 39484165, 2024). "The synthesis of fatty acids and sterols is reported to be under the control of the Ataxia Telangiectasia-mutated (ATM) axis of the DDR in glioblastoma cells and, reciprocally, saturated fatty acids and cholesterol are described to finetune the DDR activation." (PMID 34884734, 2021). "In the mouse experiment, the ATM gene was involved in the suppression of glioblastoma by the down-regulation of glioblastoma-associated genes such as the PDGFRA gene." (PMID 33353229, 2020). "It has been demonstrated that glioblastoma stem cells (GSCs) displayed a radioresistant feature which was associated with increased ATM activation." (PMID 30678233, 2019). "The DNA damage kinase ATM is known primarily as a tumor suppressor, through its role in the response to DNA double-strand breaks, and systemic loss of ATM has previously been shown to accelerate glioblastoma progression." (PMID 26984279, 2016). "Others have reported cells with deficient ATM and radioresistant glioblastoma cells express diminished p21 in vivo." (PMID 20704711, 2010). "In addition, in vitro models of glioblastoma showed that mitochondrial enzyme ATAD3A plays a role in ATM function as silencing of ATAD3A was associated with attenuation of DSB repairs and enhanced radiosensitivity." (PMID 33069104, 2021). "The ATM GV carrier and his brother in family Fam004 were diagnosed with glioblastoma at almost the same age (61 and 65 years)." (PMID 41546701, 2026). "Glioblastoma cells with high levels of intrinsic chromosomal instability and impaired ATM signaling exhibit increased radioresistance to both low- and high-LET radiation." (PMID 41402400, 2025). "Previous studies have demonstrated that ATM inhibitors potentiate cisplatin-induced apoptosis in breast cancer cells and exhibit synergistic effects with radiation therapy in glioblastoma." (PMID 40256842, 2025). "The increase in p-ATM phosphorylation in both U251 and T98G glioblastoma cells suggested its activation after LCS1269 treatment." (PMID 40649791, 2025). "Inhibitors of DDR pathways, such as ATR and ATM inhibitors, have shown promise in increasing the radiosensitivity of glioblastoma cells to high-LET radiation." (PMID 41402400, 2025). "Consistent with our findings, BEZ235 was found to potently suppress ATM and DNA-PKcs kinases, attenuate DNA damage repair, and augment therapeutic effect of radiotherapy in glioblastoma (GBM)." (PMID 37802999, 2023). "We previously reported that TP5 acts synergistically with temozolomide and irradiation in glioblastoma cells by impairing the DNA damage repair ability in tumor cells by inhibiting ATM phosphorylation." (PMID 37511490, 2023). "ATM inhibition exhibited slight sensitization effects towards temozolomide treatment in MGMT low expressing glioblastoma cells, thus encouraging further characterization." (PMID 35440003, 2022). "The MET RTK-signaling pathway leads to activation of Aurora kinase A, ATM, and p21 in glioblastoma stem-like cells resulting in increased repair and reduced apoptosis." (PMID 35158967, 2022).
glioblastoma (continued). "Particularly, the use of an ATM inhibitor, as a radiosensitizer, in malignancies known to have high levels of hypoxia, such as glioblastoma, has shown striking results in vivo." (PMID 34621741, 2021). "For ‎example, BMI1 conferred radioresistance to CD133-positive glioblastoma multiform via either ‎interaction with p-ATM, γH2AX, or global chromatin remodeling." (PMID 34268251, 2021). "ATM inhibitors are now under investigation in phase I clinical trials in patients with glioblastoma and other advanced tumors in combination with radio- and chemotherapies." (PMID 34839359, 2021). "Among the 10 patients in the ATM mut(+) group, there were 6 patients with glioblastoma and 4 patients with anaplastic astrocytoma." (PMID 32736562, 2020). "Targeting ATM is currently being investigated to enhance the radiosensitivity of other tumor types, particularly glioblastoma, but also head and neck cancers, largely focused on photon irradiation." (PMID 32481544, 2020). "The out-field control rate and OS values were comparable between the ATM mut(+) and ATM mut(−) groups in tumors with the molecular features of glioblastoma (Additional File2)." (PMID 32736562, 2020). "We showed that TP5 decreased glioblastoma cell viability and tumor growth by blocking cell cycle and increasing apoptosis through the inhibition of ATM phosphorylation." (PMID 32708903, 2020). "This is a remarkable effect, as in most experimental systems ATM is a pro-survival factor and, therefore, ATM inhibitors are used as radio-sensitizer, which was shown, e.g., for glioblastoma cells." (PMID 30323167, 2018). "Collectively, blocking the ATM/CHK2 pathway by an ATM inhibitor or a CHK2 inhibitor reduced JEV replication in human glioblastoma, lung cancer carcinoma, and neuroblastoma cell lines tested." (PMID 29868498, 2018). "Both ATR and ATM inhibition retarded spheroid growth in our studies; a similar effect on spheroid growth has previously been reported using glioblastoma cells." (PMID 28521819, 2017). "Low levels of ATM protein are a major determinant of radiosensitivity in glioblastoma, and ATM is the target of different miRNAs such as miR-100 and miR-26a." (PMID 29234674, 2017). "Bi-allelic inactivation of genes is common in cancer, including ATM in chronic lymphocytic leukemia, CDKN2A and CDKN2B in glioblastoma, and are indicative of loss of function of key tumor suppressor genes." (PMID 28234347, 2017). "In this study, we aimed to determine whether FDX1 contributes to radioresistance in human glioblastoma cells under severe hypoxia and whether it regulates key factors such as ATM, DNA-PKcs, Akt, and EGFR, which are highly expressed in cancer cells." (PMID 40244269, 2025). "Interestingly, it also correlated with mRNA expression levels of ATM, suggesting a potential role of ATM in the context of temozolomide resistance in glioblastoma cells." (PMID 35440003, 2022). "Evidence of CSCs’ resistance to radiotherapy was provided by a study that demonstrated the capacity of glioblastoma stem cells to efficiently activate the ATM serine/threonine kinase (ATM) and the DNA damage checkpoint protein kinase (Chk1) in response to ionising radiations." (PMID 31426611, 2019).
glioblastoma (continued). "In glioblastoma cells, ART was shown to induce oxidative DNA damage and DNA double-strand breaks that accumulate during the treatment period and finally activate the ATM/ATR axis and DNA damage-dependent pathways causing cell cycle inhibition and apoptotic cell death." (PMID 40564198, 2025). "High expression of MSI1, CHK2, and Rad51 and higher ATM phosphorylation was reported in radioresistant stem-like cells from patient-derived glioblastoma (GBM)." (PMID 34900673, 2021). "Since it was of special interest whether a DNA-damage response (DDR) occurs after overexpression of Survivin, we analyzed the protein levels of activated DNA-damage sensor kinase ATM in U251-MG glioblastoma cells and in SV40 TAg-immortalized human SVGp12 astrocytes." (PMID 29282022, 2017). "In conclusion, we demonstrated that FDX1 knockdown suppresses cellular radioresistance under severe hypoxia by regulating ATM, DNA-PKcs, Akt, and EGFR expression in the human glioblastoma cell line T98G." (PMID 40244269, 2025). "Nevertheless, a study investigated the in vivo propagation of patient glioblastomas via orthotopic implantation of GSCs into NOD-SCID mice and demonstrated that ATM inhibitors were able to radiosensitise both adult and paediatric tumours." (PMID 36980782, 2023). "Another ATM inhibitor, AZD1390, was verified to cross the intact blood–brain barrier, supporting the treatment of AZD1390 for glioblastoma multiforme or other brain malignancies." (PMID 37096801, 2023). "In glioblastoma cells, KU-60019 interrupts DDR signals by efficiently blocking ATM activity and downregulates AKT phosphorylation to reduce cell survival." (PMID 36765693, 2023). "Dactolisib also inhibits radiation-induced DSB repair in glioblastoma (GBM) cell lines by inhibiting DNA-PKcs and ATM and improves the radiosensitivity of radioresistant prostate cancer cell lines." (PMID 35875060, 2022). "We confirmed that transfection with miR-34a resulted in a significant decrease in the protein and mRNA levels of ATM, EGFR, Bcl2, c-Met and UGCG in glioblastoma cells." (PMID 33765907, 2021). "In our study, we found that knockdown of MINA53 decreased not only the expression of ATM and ATR but also their phosphorylation pattern in glioblastoma cells." (PMID 30333481, 2018). "MINA53 knockdown further inhibits DNA damage response by reducing the ATM/ATR-H2AX pathway activity and leads glioblastoma cells to apoptosis and death." (PMID 30333481, 2018). "A detailed analysis of the data from The Cancer Genome Atlas (TCGA) consortium set for glioblastoma multiforme (GBM), the most common and lethal primary central nervous system tumor in adults, shows that 3.2% of tumours have somatic mutations in ATR, ATM, or CHK1." (PMID 25247188, 2014). "In this study, we demonstrated that in human glioblastoma-derived cell lines, T98G and A172, under severe hypoxia (with oxygen concentrations below 0.1%), FDX1 regulates the activation of key radioresistance factors, including ATM, DNA-PKcs, Akt, and EGFR." (PMID 40244269, 2025). "Additionally, some ATM inhibitors, including AZD1390 and M3541, have been effective in radio sensitisation, increasing their potential in glioblastoma and NSCLC treatment." (PMID 40256842, 2025). "We suggested that the increased transcription of BRCA1, ATM, and DNA-PK might counteract the MGMT depletion induced by AE and TMZ treatment of glioblastoma cells." (PMID 37630276, 2023).
glioblastoma (continued). "Amongst the genes down-regulated by miR-34a, we selected five genes (ATM, EGFR, BCL2, MET, UGCG) for validation as they have been shown pre-clinically to play critical roles in cell survival and therapeutic resistance in the context of glioblastoma." (PMID 33765907, 2021). "Furthermore, MINA53 knockdown diminished DNA damage response (DDR) by reducing the ATM/ATR-H2AX pathway activity and finally led glioblastoma cells to apoptosis and death." (PMID 30333481, 2018). "This is consistent with previous findings in which ATM inhibition profoundly decreased RAD51 foci formation, increased DNA damage or γH2AX foci formation, and impaired HRR through the downregulation of RAD51 in human glioblastoma, lung, and cervical carcinoma cells." (PMID 37020276, 2023). "In our study, despite the presence of MN-γ-H2AX (+), DNA damage was not supported by either the deregulation of DDR enzymes ATM and DNA-PK or oxidative stress induction, since glioblastoma cells treated with antioxidant NAC did not revert the Ageritin-induced cytotoxicity." (PMID 35458581, 2022). "Furthermore, we discovered that ATM expression and activation under severe hypoxia are regulated through the energy sensor AMPK and the stress-responsive transcription factor Sp1, contributing to cellular radioresistance in a glioblastoma multiforme (GBM) cell line T98G." (PMID 40244269, 2025). "Quantitative RT-PCR did not reveal any change in ATM and DNA-PK transcript levels in ZAR and NULU patient-derived glioblastoma cell lines treated with 0.5 μM Ageritin for 48 h." (PMID 35458581, 2022). "In glioblastoma multiforme (GBM) cells, Bmi1 was co-purified with DSB response proteins, such as ATM and the histone γH2AX, and non-homologous end joining (NHEJ) repair proteins." (PMID 22606246, 2012).